INS (insulin)
Diseases named in the same sentence as INS in open-access papers (continued):
Sharing a sentence is not in itself a finding about the gene and the disease.
diabetes (continued). "Although the technology can be considered today the most advanced way to manage diabetes, a definitive cure could be obtained only through the biological approaches that guarantee a constant replacement of insulin such as pancreas transplants, and islet cell transplants." (PMID 33755854, 2021). "In a Turkish study, injection-related anxiety, fear of diabetes deterioration, the difficulty of dosing accuracy, dependence on others, social stigma, and reduced quality of life were the most common barriers, resulting in the patient’s resistance to initiate insulin." (PMID 34712538, 2021). "If a hypo- or hyperglycemia period is predicted, the patients could change the composition or quantity of the planned meal or the dosing of the insulin; thus, instead of trying to apply some general medical guidelines, they could gradually learn to manage diabetes in everyday life by example." (PMID 34209125, 2021). "Hence, the higher VAT isoleucine consumption observed in individuals with obesity and pre-diabetes could be a compensatory mechanism to retrain the molecular substrates as an indirect sign of inadequate insulin-mediated gluconeogenesis suppression and IR." (PMID 34071774, 2021). "Diabetes mellitus (DM), characterized with hyperglycemia, is a chronic metabolic disease resulting from dysfunction in insulin secretion and/or insulin action." (PMID 34753504, 2021). "For example, the observed association between diabetes and PC risk may be different if the use or non-use of anti-diabetic medication (e.g., metformin, insulin) had been taken into consideration." (PMID 34837975, 2021). "Wip1 depletion in mouse embryonic fibroblasts could lead to the reduction of insulin in diabetes." (PMID 34716317, 2021). "Diabetes mellitus is a group of metabolic disorders characterised by chronic hyperglycaemia, causing dysfunction in carbohydrate, protein and fat metabolism due to a complete lack of insulin or its effect." (PMID 34943445, 2021). "However, when insulin production and secretion are insufficient, alterations in metabolism occur and accumulation of glucose in the blood signals the clinical diagnosis of diabetes." (PMID 35098034, 2021). "In addition, diabetes treatment such as insulin or thiazolidinediones can also impact on bone mass." (PMID 35046898, 2021). "The heterogeneity in the relationship between obesity (as measured by BMI) and diabetes observed here could also be explained by differences in the contribution of reduced insulin secretion and reduced insulin sensitivity to the development of diabetes between various populations." (PMID 33574565, 2021). "Systemic disease diabetes mellitus (DM) is characterized by an inability of the body to either produce or effectively respond to the glucose-regulating hormone, insulin." (PMID 34925339, 2021). "Diabetes mellitus (DM) is a group of metabolic diseases characterized by high glucose and insufficient insulin secretion and/or dysfunction, which leads to chronic damage, dysfunction, and even failure of multiple organs." (PMID 34900083, 2021). "Herein, we also include the streptozotocin (STZ) induced diabetes model (STZ-induced DM) in which animals have little adipose tissue, insulin, or leptin." (PMID 34063911, 2021). "This study aimed to clarify whether Japanese patients with diabetes performed skin disinfection before insulin self-injections, as well as evaluate other factors that were associated with infection at the injection site to critically evaluate the necessity of pre-injection skin preparation." (PMID 33916158, 2021). "Diabetes mellitus (DM) refers to a group of metabolic diseases that are characterized by hyperglycemia resulting from defects in insulin secretion, insulin action, or both." (PMID 35059392, 2021). "Together, these results suggest initiating insulin therapy among those with a mean hospital glucose ≥ 140 mg/dL, rather than based on a history of diabetes or high ADG, may be associated with better outcomes for these patients." (PMID 33420311, 2021).
diabetes (continued). "Hence, the results suggest that exosomes could potentially become a valuable tool for stable and biocompatible insulin delivery in diabetes mellitus treatment alternatives." (PMID 34834285, 2021). "Thus, 2-h insulin values are among the first indicators for the development of diabetes." (PMID 33594006, 2021). "Presently, diabetes management is only based on combination of lifestyle modification and therapeutic medications to regulate blood glucose level through glucose-lowering agents or insulin replacement therapy as well as with management of cardiovascular complications." (PMID 34769045, 2021). "Therefore, melatonin may be involved in the genesis of diabetes as it induces a phase shift in insulin secretion." (PMID 34007273, 2021). "Diabetes mellitus, more commonly called diabetes, is a debilitating, long-term (or 'chronic') disease that occurs when glucose levels increase in a person's blood because their body is unable to produce any or enough of the hormone insulin, or are unable to use the insulin it produces effectively." (PMID 33850676, 2021). "The maintenance of this compensatory state in insulin secretion leads, over time, to the appearance in an initial phase of high levels of postprandial glucose, in a second phase of fasting glucose, ultimately culminating in the onset of diabetes mellitus of the type 2." (PMID 34821614, 2021). "Furthermore, pancreatic fat deposition associates with reduced insulin secretion and may be involved in the decompensation of insulin secretion and thus in the pathogenesis of diabetes." (PMID 34591793, 2021). "Insulin pump outcomes are well understood for insulin-dependent individuals, such as those with type 1 diabetics, but initiation of pump therapy immediately following a diagnosis of insulin-dependent diabetes (such as post-pancreatectomy diabetes) is a novel approach." (PMID 34064129, 2021). "Insulin dysregulation in patients with diabetes could facilitate cognitive disorders." (PMID 33816502, 2021). "Therefore, lowering of diabetes risk by coffee consumption does not involve an acute effect on the post-meal course of blood glucose, insulin or insulin resistance." (PMID 33807132, 2021). "Besides their well-recognized hypoglycemic and insulin-sensitizing effects, BB-enriched diets further improve GM homeostasis and lessen hepatic dysmetabolism, two key components of (pre)diabetes evolution." (PMID 34439410, 2021). "Furthermore, it is thought that VDBP, by regulating the amount of active vitamin D in β-cells of the pancreas, may affect insulin secretion, and thus affect the prevalence of insulin resistance and type-2 diabetes mellitus." (PMID 34011380, 2021). "Diabetes mellitus (DM) is a chronic endocrine disorder of multiple etiologies distinguished by hyperglycemia resulting from defects in insulin secretion, insulin action, or both." (PMID 33520200, 2021). "Diabetes mellitus (DM) is a group of chronic endocrine and metabolic disorders characterized by defects in insulin production, secretion, and signaling that are insufficient to maintain the right blood glucose level." (PMID 33808800, 2021). "Furthermore, routine treatment with tang-min-ling pills, a combination of ten Chinese herbal medicines, can significantly improve the insulin secretion by pancreatic β cells and reduce the level of fasting blood glucose and glycosylated hemoglobin in patients with diabetes (PMID: 23231379)." (PMID 35002950, 2021). "Diabetes mellitus (DM) is globally one of the most common chronic diseases, characterized by high blood glucose and insufficient insulin production and/or supply." (PMID 33971198, 2021). "However, we did observe a negative association between effect size and prevalence of diabetes on meta-regression, suggesting that this variant has the greatest effect in less insulin-resistant individuals." (PMID 32882372, 2021).
diabetes (continued). "Obesity is often related to meta-inflammation of the adipose tissue, which impairs insulin sensitivity in metabolic organs and triggers a decline in insulin production in the endocrine pancreas, ultimately manifesting as systemic insulin resistance, diabetes and metabolic syndrome." (PMID 34571937, 2021). "Ninety-two percent (n = 22) reported that they spent less time managing their diabetes with the closed-loop system than in the control period, and 87% (n = 21) were less worried about their glucose levels with the closed-loop system than with standard insulin therapy." (PMID 34349267, 2021). "The Joint British Diabetes Societies guideline for the management of diabetic ketoacidosis” recommends continuation of long-acting insulin analog during the initial management of DKA because it provides background insulin when the intravenous insulin is discontinued”." (PMID 36994324, 2021). "Therefore, we selected this model organism to address the issue of whether ER stress in the insulin-producing cells contributed to the pathogenesis of diabetes." (PMID 34769468, 2021). "In most studies, preoperative parameters, such as age, diabetes duration, insulin use, baseline BMI, level of fasting glucose, and HbA1c, are predictors of DM remission." (PMID 34873559, 2021). "Sphingolipids, in addition to their direct impact on the insulin signaling pathway, may be responsible for other negative aspects of diabetes, namely mitochondrial dysfunction and deficiency." (PMID 33815291, 2021). "Recently, teplizumab proved to be efficacious in delaying the onset of overt diabetes in a subgroup of beta cell autoantibody-positive individuals with dysglycaemia, providing evidence of the first immune intervention able to delay the diagnosis of diabetes and the requirement for insulin treatment." (PMID 33145642, 2021). "Notably, it has been revealed that the critical role of PIAS1 exerted important functions in controlling insulin sensitivity and thus might be potential for treatment of type 2 diabetes mellitus." (PMID 34857740, 2021). "Diabetes mellitus (DM) refers to a group of metabolic diseases that result from any defect in insulin secretion, insulin action, or both." (PMID 34041870, 2021). "Diabetes mellitus (DM) is a disease characterized by impaired metabolism of carbohydrates, proteins and fats due to insufficient secretion of insulin." (PMID 34926852, 2021). "One of the diseases most investigated today is diabetes mellitus (DM), a chronic disease characterized by hyperglycemia and insufficient insulin production by the pancreas." (PMID 34190871, 2021). "In addition, insulin directly activates phagocytic and bactericidal activity of immune cells and diabetes-induced infection susceptibility is partly mediated by impaired immune responses due to the lack of insulin signaling, as shown in rodent studies." (PMID 34795562, 2021). "It has been reported that PC(O) and PC(P) species display negative associations with area under the curve of insulin, especially in men, after an oral glucose tolerance test and that PC(O) is associated to prediabetes and diabetes when compared to individuals with normal glucose test." (PMID 34564448, 2021). "However, with the progression of diabetes, some patients may require additional insulin therapy as well." (PMID 34440499, 2021). "Furthermore, ApoA-I protected against diabetes by reducing stress-induced pancreatic β-cell apoptosis and increasing insulin secretion, and HDL attenuated islet cell inflammation in type 2 diabetes via ATP-binding cassette transporter-A1 and ATP-binding cassette transporter-G1 (ABCA1 and ABCG1)." (PMID 34095317, 2021). "In addition, arachidonic acid also can facilitate the production of anti-inflammatory lipoxins which were reported to improve insulin sensitivity and may prevent the development of diabetes." (PMID 33628839, 2021).
diabetes (continued). "They commented that most of the intervention contents were well-organized and clearly presented, except for some sections that need to be tailored to the actual situation of people with diabetes (e.g., knowledge of insulin may only be useful for those using insulin)." (PMID 34327187, 2021). "Among two main types of diabetes mellitus, type 1 DM (T1DM) is caused by the absolute insulin deficiency due to damage of insulin-producing pancreatic β cells, whereas type 2 DM (T2DM) is associated with insulin resistance, which ultimately may give rise to a relative deficiency of insulin." (PMID 34071497, 2021). "Of 90 participants with a previous diabetes diagnosis, 49 (54%) reported regular diabetes follow-up visits at a health center or with a doctor, whilst 77 (86%) reported currently taking diabetes medication of whom 68, were taking metformin, glycazide, or in combination with insulin." (PMID 36962076, 2021). "Indeed, a typical MD composition improves insulin sensitivity in patients without preexisting diabetes and this effect is probably linked to the increased amount of unsaturated FAs intake." (PMID 34205356, 2021). "Of course, the answer to this question will remain unknown until the drugs are tested in humans, but the fact that harmine alone and the harmine-exenatide combination can enhance human insulin secretion and attenuate or reverse diabetes in diabetic immunodeficient mice holds promise." (PMID 34335466, 2021). "It has been reported that the Xiaoke Pill not only exerts its antidiabetic activity by stimulation of insulin secretion mainly mediated by glibenclamide but also enhances the sensitivity of receptors towards insulin mediated by promoting adiponectin secretion in patients with diabetes." (PMID 34745311, 2021). "Moreover, excessive insulin secretion along with hyperglycemia possibly results in a negative effect on pancreatic β-cell function; this is followed by β-cell expansion failure and eventually β-cell failure and diabetes." (PMID 33809508, 2021). "In relation to diabetes and obesity, plant-based diets have shown beneficial effects as they include foods that contain high amounts of fiber, antioxidants, magnesium and phytochemicals, all of which have shown to increase insulin sensitivity and glycemic control." (PMID 33535684, 2021). "Notably, it has been revealed that PIAS1 exerted important functions in controlling insulin sensitivity and thus might be potential therapeutic target for treatment of type 2 diabetes mellitus." (PMID 34857740, 2021). "Diabetes Mellitus (DM) is a metabolic disorder characterized by hyperglycemia, resulting from the inability of the pancreas to produce enough insulin." (PMID 34945799, 2021). "Thus, an alteration in the H+/somatostatin (SST) pathway, which is involved in thyroid regulation and gastrin and insulin secretion, may trigger not only achlorhydria but also hypothyroidism and diabetes." (PMID 34944008, 2021). "In the type 2 diabetes group, a total of 21 (88%) had changes in their diabetes therapy from baseline to follow up (insulin; sodium-glucose cotransporter 2 inhibitor (SGLT2i); glucagon-like peptide-1 receptor agonist (GLP1-RA); metformin) which might have influenced our results." (PMID 34966359, 2021). "Diabetes mellitus (DM) is a metabolic disorder characterized by a persistent rise in the blood glucose level resulting from defects in cellular insulin function, secretion, or both, which affects millions of people every year." (PMID 34527069, 2021). "Type 2 diabetes mellitus (DM) is a heterogeneous abnormality characterized by insulin resistance and defective insulin secretion." (PMID 34207835, 2021). "Management of patients with type 2 diabetes mellitus (T2DM) may involve insulin therapy." (PMID 34712538, 2021).
diabetes (continued). "Hence, key players of the diabetes- breast cancer crosstalk include insulin and its binding to insulin receptor which triggers the insulin pathway, and which subsequently leads to the activation of PI3K-AKT and MAPK pathways, and HIF1 signaling via mTOR pathway." (PMID 34225729, 2021). "Diabetes mellitus (DM) describes a group of metabolic disorders characterized by hyperglycemia and defects in insulin secretion and/or insulin action." (PMID 33728350, 2021). "The onset and progression of diabetes mellitus (DM) is crucially determined by the deterioration of the glucose-stimulated insulin secretion (GSIS) of pancreatic β-cells." (PMID 33672062, 2021). "We aimed to analyze the effect of PIs on insulin sensitivity and the onset of diabetes mellitus (DM) in patients with HIV." (PMID 34790115, 2021). "Diabetes mellitus (DM) is a multifactorial disease, where the body becomes unable to utilise or produce a sufficient amount of insulin to match the body's needs." (PMID 34497644, 2021). "Even in the recent 63 page publication in the Lancet from the Lancet Commission on Diabetes that embodies 4 years of extensive work to make recommendations to improve clinical practice, carbohydrates are only mentioned once and only in relation to adjusting insulin doses." (PMID 34434951, 2021). "The Diabetes Prevention Trial-Type 1 (DPT-1) was the first randomized, multicenter trial that asked whether T1D could be prevented or delayed in high risk individuals by insulin administration prior to disease onset." (PMID 33418839, 2021). "Therefore, patients with diabetes on SGLT2 inhibitors require lower doses of insulin, which may further promote ketogenesis." (PMID 33581735, 2021). "Insulin use was significantly associated with both outcomes, possibly because diabetes management is more burdensome for those who use insulin than for those who do not, which could be taken into account in their decision to adopt a burdensome RDM regime." (PMID 33439263, 2021). "Moreover, INS mutation increases ER stress and hampers proliferation of β-cells but without increased apoptosis promoting diabetes development in patients." (PMID 34079523, 2021). "In the context of these studies, our results suggest that as a compensatory factor, reduced insulin clearance may be a biomarker for diabetes, but not a primary causal factor." (PMID 34206745, 2021). "As in type 1 diabetes mellitus (T1DM), progressive loss of pancreatic islet cells occurs in CFRD; however, unlike T1DM, beta cell autoimmunity markers are negative and the onset of diabetic ketoacidosis (DKA) is extremely rare since there is a minimal insulin production." (PMID 34078438, 2021). "Diabetes mellitus (DM) is generally a complex disease that affects all races and ethnic groups due to improper functioning of insulin, secretion of insulin, or can be a result of both and is the major cause of mortality of death worldwide." (PMID 34540481, 2021). "Therefore, we hypothesized that CR maintains blood insulin levels in the late stage of diabetes with an elevation in insulin secretion and/or a reduction in IDE expression." (PMID 33916828, 2021). "The presence of this alteration at the beginning of the disease, according to the authors, might be related to the early process of collagen glycosylation, which is stabilized and stopped when diabetes mellitus is diagnosed and insulin therapy is promptly begun." (PMID 33530418, 2021). "Type 1 diabetes mellitus is a pathological condition in which insulin secretion is impaired due to the destruction of pancreatic β-cells, in contrast to type 2 diabetes mellitus, wherein genetic and environmental factors are responsible for insulin resistance and decreased insulin secretion." (PMID 34681566, 2021).